IFNG (interferon gamma)
Diseases named in the same sentence as IFNG in open-access papers (continued):
Sharing a sentence is not in itself a finding about the gene and the disease.
cerebral malaria (71 papers, 2007 to 2025). A sequestration of Plasmodium falciparum in the brain, which can cause coma and/or seizures. "Another study showed higher serum Interferon gamma levels in children carrying the TLR9-1237-C allele with cerebral malaria, indicating that enhanced TLR9 mediated immune responses are also relevant inside the CNS." (PMID 22577991, 2012). "Interestingly, IFNγ and TNFα have been linked to cerebral malaria progression by acting on brain endothelial cells, thus promoting their activation and/or apoptosis." (PMID 31223430, 2019). "Furthermore, regardless of genotype, relative levels of cytokines, particularly the ratio of IL4 to IFNG, are more strongly associated with protection from cerebral malaria than levels of any single cytokine alone." (PMID 25192715, 2014). "Similar outcomes were observed in a mouse model where high proportions of Vγ9Vδ2 T cells were associated with increased plasma levels of pro-inflammatory cytokines, notably TNF alpha and IFNγ, leading to cerebral malaria." (PMID 38827744, 2024). "A large quantity of interferon gamma (IFN-γ) is secreted by NK cells that play a critical role in immune-mediated brain damage in experimental cerebral malaria." (PMID 35735506, 2022). "Cerebral malaria in this model was shown to be highly promoted by CD8+ T cells that adhere to activated brain endothelium as a consequence of TH1-dependent IFNγ production." (PMID 27311945, 2016). "And in vivo studies have demonstrated that the cytokines TNFα and IFNγ are essential for the development of cerebral malaria by inducing the expression of the adhesion molecule ICAM-1 and nitric oxide (NO)." (PMID 24550911, 2014). "Another study on TLR9 -1237 SNPs showed higher serum Interferon gamma levels in children with cerebral malaria, indicating that enhanced TLR9 mediated immune responses are also relevant inside the CNS." (PMID 22662111, 2012). "While further work needs to be done to establish the role of CD4+ and CD8+ T cells in the brain of infected pups, as they are required for experimental cerebral malaria;42 both cell types also make IFNγ that is essential to experimental cerebral malaria in adult mice." (PMID 36131528, 2022). "It has been reported that the absence of functional IFNα/β receptor pathway and IFNγ pathway reduces murine experimental cerebral malaria-associated brain pathology induced by blood-stage PbANKA infection." (PMID 34899708, 2021). "Indeed, although administration of low doses of IL-1 was originally found to protect mice against cerebral malaria, through T-cells and IFNγ, postmortem analysis detected increased IL-1β in human brains with cerebral malaria." (PMID 28448579, 2017). "The high IFNγ production of different splenic lymphocyte subsets at an early time point of PbA infection and the enhanced susceptibility for cerebral malaria symptoms in the absence of IL-22 might be due to an enhanced TH1 response during PbA infection." (PMID 27311945, 2016). "Other inflammatory cytokines, such as interferon gamma (IFN-γ), interleukin-6 (IL-6), and IL-1β, are also elevated in adults and children with cerebral malaria, with circulating concentrations ranging between 0.01 and 1 ng/mL." (PMID 36036514, 2022). "Comparing the proportion of IFNγ+, IFNγ+ IL10+ and IL10+CD4+ T cells in patients with uncomplicated and severe cerebral malaria, we detected a trend towards a decreased proportion of IL10+CD4+ T cells in patients with severe cerebral malaria." (PMID 27802341, 2016). "There is accumulating evidence that the pathogenesis of cerebral malaria is due to an immune-pathological reaction giving rise to excessive production of cytokines such as tumor necrosis factor-alpha (TNF-α) and interferon gamma (IFN-γ)." (PMID 25886020, 2015).
cerebral malaria (continued). "In particular, the balance of inflammatory Type I cytokines, such as interferon gamma (IFNG) and tumour necrosis factor (TNF), with Type II cytokines, e.g., interleukin 4 (IL4) and IL10, is thought to determine the lethality of cerebral malaria." (PMID 25192715, 2014). "Moreover, IFNγ production has been established to be essential to the development of ECM pathology, as both IFNγ-/- and IFNγR-/- mice are completely protected from developing cerebral malaria." (PMID 25768944, 2015).
neuroblastoma (71 papers, 2003 to 2025). Neuroblastoma (NB) is the most common solid, extracranial childhood tumor. "Subsequently, we examined the functional role of NKG2D in human CD8+ T cell-mediated killing of neuroblastoma cells through an in vitro IFNγ ELISA assay conducted in the presence of an NKG2D-blocking antibody." (PMID 40552293, 2025). "QSOX2 was found to regulate the sensitivity of neuroblastoma cells to interferon-gamma-induced apoptosis, also suggesting a role in immune regulation in GBM." (PMID 41226720, 2025). "In order to evaluate the potential role of immune checkpoint pathways in the reduction of ADCC over time, the effects of IFNγ treatment on PD-L1 and PD-L2 expression as well as Stat1 activation in neuroblastoma cells was evaluated." (PMID 36525420, 2022). "GRP-R mAb-1 mediated ADCC effects on neuroblastoma cells and induced release of IFNγ by NK cells under co-culture conditions in vitro." (PMID 36525420, 2022). "Our results suggest that IFNγ induces the expression of PD-L1 via activation of Stat1 in neuroblastoma." (PMID 36525420, 2022). "In order to confirm that IFNγ induced PD-L1 via Stat1, we treated six neuroblastoma cell lines with IFNγ at two doses (1 and 10 ng/ml) for 24 hours." (PMID 36525420, 2022). "We then examined the expression of PD-L1 in six neuroblastoma cell lines and found that the expression of PD-L1 was induced by IFNγ in a dose-dependent response in the levels of both protein and mRNA, in all except SH-SY5Y cell line." (PMID 36525420, 2022). "In Neuroblastoma, expression of PD-L1 is both constitutive and inducible by different mechanisms such as IFNG-induced signaling, with expression levels ranging from 14% to 70% in patients." (PMID 36700232, 2022). "Depletion of GBP1 in an IFNγ primed environment also inhibited virus replication in human neuroblastoma SH-SH5Y cells." (PMID 35663470, 2022). "FAS expression on the neuroblastoma cell surface was flow cytometrically assessed after 24 h of IFNG treatment." (PMID 34771652, 2021). "Cultured neuroblastoma cells were exposed to IFNG concentrations ranging from 1 to 15 ng/mL, which was up to 15 times higher than IFNG amounts released by the CAR T cells in coculture experiments." (PMID 34771652, 2021). "Cytokine (IFNG) release from CAR T cells after coculture with the three selected neuroblastoma cell lines was quantified by ELISA." (PMID 34771652, 2021). "In previous studies, exposure of several cultured human malignant glioma cell lines, primary neurons, and a neuroblastoma cell line to IFNγ reduced TRP levels in culture medium accompanied by increased IDO1 expression and KYN production." (PMID 32117235, 2020). "The checkpoint inhibitor PD-L1 is expressed on mouse and human neuroblastoma and is up-regulated in response to interferon gamma (IFNγ) exposure or infiltration of T cells into the tumor." (PMID 29377881, 2018). "The same synergistic effect was observed in N2a neuroblastoma cell line, where combined treatment with IFNγ and 5-aza led to higher gene induction of H2-D1/L gene expression than the treatment with either one individually." (PMID 29970123, 2018). "We show that PD-L1 is expressed on mouse and human neuroblastoma and is up-regulated following interferon gamma (IFNγ) treatment or T-cell tumor infiltration." (PMID 29377881, 2018). "In summary, contact-dependent production of IFNγ stimulates the presentation of peptide/MHC I complexes at the cell surface of neuroblastoma cells, for antigen-specific presentation and recognition by PRAMESLLQHLIGL/A2-restricted CTLs." (PMID 26452036, 2015). "To confirm that IFNγ was required for the MHC I upregulation in neuroblastoma cells we used IFNγ blocking antibodies during the co-culture." (PMID 26452036, 2015).
neuroblastoma (continued). "We also show that IL-6, similar to the neuroblastoma/monocyte CM, significantly suppresses release of IFNγ by IL-2-stimulated NK cells." (PMID 23982484, 2013). "We discovered that lenalidomide, at a clinically achievable concentration, prevented the suppression of IL-2-mediated activation of NK cell cytotoxicity, ADCC, and IFNγ secretion by neuroblastoma/monocyte CM." (PMID 23982484, 2013). "CM from neuroblastoma/monocyte co-cultures contains IL-6 and TGFβ1 that suppress IL-2 activation of NK cell cytotoxicity and IFNγ secretion." (PMID 23982484, 2013). "Thus, in marked contrast to IL12/15 failure to induce IFNγ production, NK cells from patients with neuroblastoma robustly upregulated granzyme B in response to cytokine." (PMID 36276144, 2022). "Interestingly, an IFNG-mediated increase in FAS expression only occurred in NB-1 neuroblastoma cells, which already expressed high FAS levels before IFNG treatment." (PMID 34771652, 2021). "In a co-culture killing assay, we showed that 3 out of 6 neuroblastoma organoids could activate TEG002 as measured by IFNγ production." (PMID 34575700, 2021). "Indeed, we observed FAS upregulation in neuroblastoma cells, but only in the presence of very high IFNG concentrations, which would be unrealistic in an in vivo setting." (PMID 34771652, 2021). "We tested whether IFNG treatment could upregulate FAS expression on our selected neuroblastoma cell lines." (PMID 34771652, 2021). "In neuroblastoma patients for instance, gene set enrichment analysis has shown that MYCN levels negatively correlate with genes involved in different immune system pathways, especially those associated to interferon gamma and phagocytosis." (PMID 34195095, 2021). "Therefore, expanded TILs post REP retain capacity to produce interferon gamma if suitably activated, and retain the capacity of freshly isolated T cells to migrate towards neuroblastoma cell lines." (PMID 31398192, 2019). "In a nonimmunogenic, aggressive neuroblastoma model (AgN2a), PD-L1 expression is neither significant nor up-regulated in response to IFNγ and T-cell infiltrates, making the tumor more susceptible to vaccine therapy." (PMID 29377881, 2018). "In a nonimmunogenic, aggressive mouse neuroblastoma model (AgN2a), PD-L1 expression is neither significant nor up-regulated in response to IFNγ and T-cell infiltrates, making the tumor more susceptible to vaccine therapy." (PMID 29377881, 2018). "Thus, we confirmed in primary neuroblastoma cells the ability to upregulate MHC I surface levels in response to IFNγ." (PMID 26452036, 2015). "We hypothesized that secretion of IFNγ, which can be locally produced by activated immune cells and stimulates antigen presentation in neuroblastoma cells, may trigger the enhanced MHC I expression triggered by activated NK cell contact." (PMID 26452036, 2015). "Incubation with recombinant IFNγ could enhance MHC I surface expression on neuroblastoma cells and subsequently increased PRAMESLLQHLIGL/A2-restricted CTL recognition of both GIMEN and Sy5y+A2 cells." (PMID 26452036, 2015). "Furthermore, NK cells induce MHC I upregulation in neuroblastoma through contact-dependent secretion of IFNγ." (PMID 26452036, 2015). "We found IFNγ to play a major role in MHC I upregulation on neuroblastoma cells." (PMID 26452036, 2015). "Thus, cell-cell interactions between activated NK cells and neuroblastoma cells elicits the production of IFNγ." (PMID 26452036, 2015). "Additionally, consistent with the concept that IFNγ could increase MHC-I expression in neuroblastoma, the MHC score was substantially and positively correlated with the activity of interferon receptors." (PMID 36605200, 2022). "One could consider IFNγ treatment of neuroblastoma patients prior to cellular immunotherapy." (PMID 26452036, 2015). "Finally, we asked whether primary patient-derived neuroblastoma cells do upregulate MHC I upon IFNγ exposure, as this data would validate our findings in neuroblastoma cell lines." (PMID 26452036, 2015).
neuroblastoma (continued). "Additionally, we investigated the direct effect of IFNγ on neuroblastoma MHC I levels." (PMID 26452036, 2015). "PARP4, stimulated by interferon gamma (IFN-γ) and tumor necrosis factor-alpha (TNF-α), mediates apoptosis in human neuroblastoma cells." (PMID 41460301, 2025). "To investigate the functional characteristics of the organoids which could determine their susceptibility to TEG002, we divided the neuroblastoma organoids into two groups according to the IFNγ production by TEG002 (i.e., Activation versus No Activation) and compared their transcriptomic profiles." (PMID 34575700, 2021). "Inclusion of lenalidomide in cultures containing 50 % neuroblastoma/monocyte CM prevented the suppression of IL-2-induced direct cytotoxicity, ADCC, and IFNγ secretion." (PMID 23982484, 2013). "In summary, our study demonstrates that the microenvironmental milieu of neuroblastoma cells includes IL-6 and TGFβ1, which suppress IL-2 activation of NK cells for direct cytotoxicity, ADCC, and IFNγ secretion." (PMID 23982484, 2013). "Using neuroblastoma as a model, CancerPAM analysis of tumour sequencing data identifies optimal knock-in sites for pro-inflammatory cytokines (CXCL10, CXCL11, IFNG), and CancerPAM rankings correlate strongly with target-site specificity and knock-in efficiency, validating its predictive performance." (PMID 41366257, 2025). "In our mouse model, splenocytes with APCs induced stronger IFNγ production and cytotoxicity against neuroblastoma cells than those without APCs." (PMID 40552293, 2025). "Similar to our findings, neuroblastomas treated with the boiling form of histotripsy (boiling histotripsy) demonstrated greater PDL-1 expression within the TME and decreased IL-10 and increased IFNγ systemic concentrations." (PMID 37893110, 2023). "Two studies showed that cytokines like tumor necrosis factor alpha (TNFα), Interleukin (IL)-1 and interferon gamma (IFNγ) induce neutrophil adhesion to SK-N-SH and LAN-1 neuroblastoma cell lines by upregulating intercellular adhesion molecule-1 (ICAM-1) expression." (PMID 38087370, 2023). "Patients with neuroblastoma failed to produce IFNγ under conditions that robustly produced IFNγ by NK cells from healthy pediatric or adult controls." (PMID 36276144, 2022). "We did not observe FAS upregulation on neuroblastoma cells after exposure to IFNG concentrations equivalent to those produced by T cells upon in vitro tumor cell encounter." (PMID 34771652, 2021). "IFNG release was proportional to antigen levels expressed on the neuroblastoma cells, independent of the costimulatory domain used." (PMID 34771652, 2021). "Neuroblastoma cell/monocyte co-cultures generated CM that contained IL-6 and TGFβ1 and that suppressed IL-2 activation of NK cells for direct cytotoxicity, ADCC, and IFNγ secretion." (PMID 23982484, 2013). "As with experiments testing neuroblastoma/monocyte CM, we discovered that lenalidomide, at clinically achievable concentrations, prevented IL-6 suppression of IL-2-mediated activation of NK cell cytotoxicity, ADCC, and IFNγ secretion." (PMID 23982484, 2013). "The other two neuroblastoma cell lines, with the lower levels of L1CAM target expression, exhibited only very low FAS levels on the cell surface that were only slightly upregulated by IFNG treatment regardless of concentration." (PMID 34771652, 2021). "Indeed, both IFNγ and IP10 (Interferon-induced protein 10) were present in supernatants of activated NK-neuroblastoma cell co-cultures but absent in culture supernatants of neuroblastoma cells co-cultured with B cells or naive NK cells." (PMID 26452036, 2015).
ZIKV infection (70 papers, 2016 to 2026). "Zika patients in the acute phase of infection had increased mRNA levels of IFNα, IFNβ and IFNγ in their peripheral blood compared to healthy controls, and ZIKV infection was also associated with high mRNA levels of TLR3." (PMID 31635238, 2019). "Here the authors show roles for CD4+ T cells and the associated IFNγ signaling in antibody-mediated resistance to Zika virus infection." (PMID 30087337, 2018). "Grifoni and colleagues elucidated in-depth characterization of human CD8+ T cells responding to ZIKV infection that are characterized by a polyfunctional IFNγ signature with upregulation of TNFα and related activation markers." (PMID 35793354, 2022). "In general, ZIKV infection elicited rapid increase in serum cytokines and chemokines (specifically IFNγ, TNFα, MCP-1, IL-15, IL-10, IL1RA, MIP-1β), with responses peaking around 1–2 days post-infection." (PMID 34120576, 2021). "In that scenario, we also wanted to evaluate the role of IFNγ, as previous analysis have pointed to the collaboration between antibodies and this cytokine in protection against ZIKV infection." (PMID 34835021, 2021). "Since a selective deficiency in perforin production did not significantly impair virus control in the CNS, we are led to assume that IFNγ alone or in combination with perforin are required for CD8 T cells to control ZIKV infection in this organ." (PMID 32973802, 2020). "Two cytokines that contributed substantially to the cytokine profile clustering in ZIKV infection of stromal MSCs and PNT1a cells were IFNγ and IP-10." (PMID 33378361, 2020). "While IFNγ is canonically made by immune cells, our data show that multiple prostate cell types produce IFNγ upon ZIKV infection." (PMID 33378361, 2020). "Protective adaptive immunity to ZIKV has been mainly attributed to neutralizing antibodies but the role of cytotoxic CD8+ T cells, as well as CD4+ T cells and IFNγ signaling in antibody-mediated resistance to ZIKV infection has also been suggested." (PMID 32194996, 2020). "The IFNγ response in the CD4+ T cells from the DENV 12M group before ZIKV infection is remarkable (left)." (PMID 32463814, 2020). "We showed that MAIT cell IFNγ production following in vitro ZIKV infection also depended on IL-12 and IL-18." (PMID 29357366, 2018). "Another study using AG129 in primary ZIKV infection was inconclusive determining the role of IFNγ in resistance." (PMID 30087337, 2018). "MAIT cells from healthy individuals consistently produced IFNγ in response to in vitro ZIKV infection." (PMID 29357366, 2018). "Our results point to an essential contribution of IFNγ signaling in the resistance to ZIKV infection." (PMID 30087337, 2018). "The frequencies of CD3+CD8+IFNγ+ T cells after ZIKV infection that were restimulated ex vivo with DENV2-E4–12, DENV2-E7–15, and DENV2-NS3347–355 were 2.92 ± 0.18%, 0.56 ± 0.1%, and 0.55 ± 0.11%, respectively (two independent experiments)." (PMID 29129917, 2017). "In our study, ZIKV infection was associated with the upregulation of IFNB, IFNL, and IFNG at the transcriptional levels, but significant protein production by ZIKV-infected DSCs was only observed for IFN-γ and IFN-γ-stimulated genes such CXCL10." (PMID 36483552, 2022). "MAIT cell IFNγ response to ZIKV infection was TCR independent, but IL-12 and IL-18 dependent." (PMID 29357366, 2018). "We also report that MAIT cells can produce IFNγ in response to in vitro ZIKV infection." (PMID 29357366, 2018). "Notably, CD4+ T cell and B cell responses and IFNγ signaling were fundamental to protection against primary ZIKV infection." (PMID 30087337, 2018). "Type II IFN (IFNγ) are key inducers of proinflammatory cytokines such as IRF1, IFIT1, CXCL10 and crucially, known cellular receptors for ZIKV infection such as AXL, Tyro3, and DC-SIGN." (PMID 35536870, 2022).